LEP (leptin)
Diseases named in the same sentence as LEP in open-access papers (continued):
Sharing a sentence is not in itself a finding about the gene and the disease.
cognitive decline (continued). "Population studies reveal that chronic exposure to PM2.5 may accelerate cognitive decline through various complex pathways centering on leptin resistance." (PMID 41515969, 2025). "This Aβ-mediated inhibition of hypothalamic neuropeptide Y (NPY) neurons may induce a catabolic state with low leptin, contributing to further neurodegeneration and cognitive decline." (PMID 41516046, 2025). "Finally, translational challenges from animal models to humans persist, and while therapies like leptin sensitizers show promise, their effectiveness in treating cognitive decline needs further research for clinical application." (PMID 39594988, 2024). "Interventions that manage BMI and leptin concentrations could mitigate cognitive decline during and after pregnancy in this population." (PMID 39203886, 2024). "Also, higher serum LEP levels at baseline are protective against cognitive decline after 5 years of follow-up in the healthy older population." (PMID 35928129, 2022). "However, other studies have not supported these findings or even found an inverse relationship between serum leptin and cognitive decline and dementia." (PMID 30893833, 2019). "First, body fat contains sex hormones and leptin, which may contribute to prevention of cognitive decline in older adults." (PMID 29096612, 2017). "In healthy elderly subjects, plasma leptin levels are positively correlated with grey matter volume of several brain regions, including the hippocampus, and inversely correlated with aging-related cognitive decline." (PMID 29156608, 2017). "Finally, our findings suggest that TUG test performance, inspiratory respiratory muscle strength, and lower blood levels of leptin may indicate cognitive decline in community-dwelling older women." (PMID 38684691, 2024). "Also how the dysregulated adiponectin and leptin are developing cognitive decline." (PMID 37363537, 2023). "First, the hormone leptin, secreted mainly from the adipose tissue, might contribute to regulate the hippocampal synaptic plasticity and to slow the cognitive decline, as it is established that the hormone leptin contributes to enhance memory performance in rodents." (PMID 35330705, 2022). "We are proposing that since leptin has been considered to be a cognitive enhancer, whereby cellular leptin acts on hippocampal cells (as one example) and improves performance in object recognition; leptin resistance and subsequent higher plasma levels should induce cognitive decline." (PMID 25251414, 2014). "Thus, decrease in leptin effect could lead to cognitive decline." (PMID 33542352, 2021). "Nevertheless, the mechanistic pathway linking plasma leptin and AD-related cognitive decline is not yet fully understood." (PMID 38700863, 2024). "Conversely, higher levels of leptin in the elderly are shown to be protective against cognitive decline, independent of comorbidities and body fat." (PMID 38892118, 2024). "Plasma leptin levels did not predict cognitive decline or cortical thinning, irrespective of participants having Aβ (+) or Aβ (–) status." (PMID 38534454, 2024). "Consistent with our findings, higher leptin levels in older adults have been shown to be related to less cognitive decline, regardless of comorbidities and body fat levels." (PMID 38684691, 2024). "In contrast to adiponectin, plasma leptin levels did not predict cognitive decline or cortical thinning either in participants with Aβ (+) or in those with Aβ (−) status." (PMID 36329496, 2022). "Baseline plasma leptin levels were not significant in predicting cognitive decline and progress in cortical atrophy regardless of Aβ pathology." (PMID 36329496, 2022). "A few human observational studies also reported a protective effect of leptin on cognitive decline and dementia in nonobese individuals." (PMID 29867443, 2018).
cognitive decline (continued). "This work has some limitations: body fat and other parameters (e.g., insulin, testosterone, oestrogen levels), which may also play an important role on leptin, adiponectin and cognitive decline, were not collected." (PMID 38686200, 2024). "However, despite the connections between leptin and AD, the data does not support leptin as an indicator for cognitive decline onset." (PMID 38534454, 2024).
hypothyroidism (54 papers, 2009 to 2025). Abnormally low levels of thyroid hormone. "Leptin levels have been found to fall with weight loss, and this has been observed to significantly ameliorate hypothyroidism." (PMID 38618433, 2024). "Multiple endocrine abnormalities such as growth hormone deficiency, hypothyroidism, hypogonadism, and leptin resistance are also seen in PW patients, due to hypothalamus–pituitary–gonadal axis dysregulation." (PMID 38397265, 2024). "Hypothyroidism in utero also caused an increase in perirenal adipose tissue mass and plasma leptin concentration." (PMID 28144955, 2017). "TSH stimulates leptin secretion, and hypothyroidism is linked to increased weight gain." (PMID 36520252, 2023). "Due to the primary role of leptin in this process, the systemic inflammatory state associated with overweightness suggests an elevated risk of autoimmune thyroid diseases, including Hashimoto’s thyroiditis, which is the primary cause of hypothyroidism." (PMID 38260160, 2023). "Weight loss was achieved in adolescents with DS in spite of the presence of potential obesogenic physiologic characteristics associated with DS including hypotonia, hypothyroidism, decreased resting energy expenditure, increased leptin, and chronotropic incompetence." (PMID 36405842, 2022). "Although the exact mechanism by which hypothyroidism causes weight gain is still a matter of investigation, several hypotheses such as increased activity of deiodinase, role of leptin, inflammatory mediators from adipocytes have been postulated." (PMID 33425213, 2020). "These factors encompass a decreased resting metabolic rate, endocrine abnormalities such as hypothyroidism, and variations in leptin levels." (PMID 41153480, 2025). "In hypothyroidism, thyroid stimulation hormone (TSH) is favorably linked with glycated hemoglobin (HbA1c), triglyscride (TG), TyG index, BMI, WC, leptin, ANGPTL8, hs-CRP, and IR." (PMID 39252284, 2024). "A positive, strong correlation was observed with metformin treatment, whereas other parameters showed moderate (TG, insulin, BMI, waist circumference, S100B, and LEP) and weak (hypothyroidism and VIS_E) positive correlation." (PMID 37960185, 2023). "They analysed leptin, adiponectin and resistin in children with untreated Graves’ disease and hypothyroidism in Hashimoto’s thyroiditis." (PMID 35399935, 2022). "The synergistic effect of hypothyroidism and hypothalamic leptin resistance is a possible mechanism." (PMID 35742214, 2022). "Similar results were observed in women with hypothyroidism: a decrease in the levels of T3, fT3, and T4 and an increase in the level of leptin." (PMID 34681131, 2021). "Postmenopausal women with subclinical or overt hypothyroidism (OH) have been demonstrated to have higher levels of leptin." (PMID 33305315, 2021). "Although hypothyroidism has been shown to increase leptin levels, the physiological mechanisms for the TH-induced alterations in serum leptin levels have not been completely elucidated." (PMID 30705778, 2019). "The serum leptin levels of patients with hypothyroidism (28.4±4.1 ng/ml) were significantly higher than the controls (19.1±3.2 ng/ml) (P<0.01), whereas patients with hyperthyroidism had lower levels (10.7±1.2 ng/ml) (P<0.01)." (PMID 30705778, 2019). "In patients with hypothyroidism, thyroxin treatment significantly decreased serum leptin levels to 20.6±2.1 ng/ml (P<0.05)." (PMID 30705778, 2019). "Hypothyroidism in the sheep fetus resulted in an asymmetric pattern of organ growth, pancreatic beta cell hyperplasia, and elevated plasma insulin and leptin concentrations." (PMID 28144955, 2017). "Plasma leptin concentration was increased by fetal hypothyroidism and pancreatic beta cell proliferation showed a bimodal response to leptin exposure in vitro." (PMID 28144955, 2017).
hypothyroidism (continued). "Although further studies are necessary to clarify the effects of these hormones in the testis during hypothyroidism, the goal of this review is to highlight the current knowledge regarding leptin and TH in the testis." (PMID 25505448, 2014). "The likely mechanism of the pups’ primary hypothyroidism is decreased leptin signaling in the thyroid." (PMID 23181022, 2012). "Looking for a potential role of leptin in the metabolic consequences of hypothyroidism, leptin was infused, and it was found that glucose disposal was recovered." (PMID 21941681, 2011). "The blood levels of metabolic hormones, including adipokines (insulin, adiponectin, leptin, apelin, chemerin, resistin, visfatin, vaspin, and omentin), in patients with thyroid dysfunction (hyperthyroidism and hypothyroidism) and correlations between thyroid and metabolic hormones." (PMID 40563510, 2025). "Further studies are needed to determine whether hypothyroidism promotes EC by increasing leptin levels." (PMID 30705778, 2019). "The effects of hypothyroidism on development of the fetal endocrine pancreas may be mediated indirectly by other hormones, such as insulin, leptin and IGFs." (PMID 28144955, 2017). "Therefore, in the present study, we evaluated serum levels of adiponectin, resistin and leptin, as well as cholesterol and triglycerides in patients with newly diagnosed patients with hypothyroidism and hyperthyroidism." (PMID 27193069, 2016). "Hypothyroidism significantly reduced body weight and elevated the plasma leptin concentration." (PMID 25333636, 2014). "Additionally, hypothyroidism compromises the intracellular integration of leptin signaling specifically in the arcuate nucleus." (PMID 25505448, 2014). "Therefore, one possible explanation to decreased insulin responsiveness in hypothyroidism, according to the authors of this study, includes a dysregulation of leptin action at the hypothalamus." (PMID 21941681, 2011). "The identification of factors that lead to hypothyroidism in some, but not all, leptin-deficient patients will provide better understanding of the roles of leptin on the hypothalamic-pituitary-thyroidal axis." (PMID 19889232, 2009). "Finally, the study population included patients with poor glycemic and lipidic control, as well as with other comorbidities such as gastrointestinal and emotional conditions and hypothyroidism which could affect the ghrelin–leptin axis." (PMID 41441006, 2025). "Detection of high maternal serum leptin levels may be a reason for subclinical hypothyroidism." (PMID 35510203, 2022). "From studies both in vivo and in vitro, the effects of hypothyroidism on pancreatic beta cell proliferation and mass before birth appear to be due not only to the deficit in circulating thyroid hormones, but also to coincident changes in insulin and leptin exposure." (PMID 28144955, 2017). "Therefore, it seems that leptin serum level increased in patients with hypothyroidism." (PMID 24575288, 2013). "Likewise, animal studies on hypothyroidism rats during pregnancy have shown reduced proliferation of cytotrophoblast cells and invasion of extravillous trophoblast cells, as well as decreased expression of cytokines, matrix metalloproteinases, nitric oxide synthase, and leptin." (PMID 41282300, 2025). "Increased leptin secretion, changes in GLUT4 translocation and elevated serum free fatty acids were postulated to contribute to IR in hypothyroidism." (PMID 40100858, 2025). "Leptin levels were found to correlate with TSH levels and were elevated in patients with hypothyroidism." (PMID 38116309, 2023). "Seven of the examined variables (hypothyroidism, waist circumference, HDL, ADIPO, S100B, LEP, and LEP_R) correlated with sex; therefore, we decided to study women and men groups separately." (PMID 37960185, 2023).
hypothyroidism (continued). "Although hypothyroidism occurs, the HPT response to leptin administration is preserved in SL offspring, reinforcing selective leptin resistance in the ARC, the nucleus involved in satiety behavior, but not in the PVN." (PMID 35631188, 2022). "Concordantly, the “satiety hormone” leptin showed significant plasma elevations under the PTU treatment, and these elevations regressed to normal levels after hypothyroidism reversal." (PMID 25333636, 2014). "Results show that serum leptin and thyroid stimulating hormone are significantly correlated in patients with metabolic syndromeirrespective of with and without hypothyroidism." (PMID 40255297, 2025). "For its part, the effect of hypothyroidism on the serum concentration of leptin in hypothyroid animals is confused because some studies have showed a decrease in the circulating leptin of hypothyroid rats, while others have not." (PMID 28133606, 2017). "So it’s not a surprise to see reduced leptin levels in patients with hyperthyroidism (low BMI), but elevated in patients with hypothyroidism (high BMI)." (PMID 27193069, 2016). "It would have therefore been acceptable if leptin levels had increased post-thyroidectomy as a result of the occurrence of intentional hypothyroidism, as we do not replace our thyroid cancer patients with thyroid hormones prior to radioactive iodine ablation." (PMID 24867470, 2014). "But the most studies have not shown significant changes in leptin levels in hypothyroidism and hyperthyroidism disorders." (PMID 22007338, 2011). "Thus, monitoring of leptin levels amongmetabolic syndrome patients with and without hypothyroidism is relevant." (PMID 40255297, 2025).
breast tumor (53 papers, 2006 to 2024). "Multivariable-adjusted associations of body fatness measures with LEP protein and LEP gene expression in breast tumor tissues." (PMID 35846306, 2022). "Compared to normal adipocytes, the cancer-associated adipocytes (CAA) are able to secrete high leptin levels, which trigger the invasiveness of breast tumor cells." (PMID 33562737, 2021). "We show a positive association between FGFR1 and leptin protein copy number in primary breast tumors." (PMID 33019728, 2020). "The association between leptin serum levels and the size of breast tumors has been summarized in a recent review; higher leptin levels are related to a more aggressive disease, presence of metastasis and a lower survival rate mostly in obese patients." (PMID 27187365, 2016). "Accordingly, HNK treatment inhibited breast tumor growth in diet-induced-obese mouse model (exhibiting high leptin levels) in a manner associated with activation of miR-34a and inhibition of MTA1-β-catenin." (PMID 26036628, 2015). "Overexpression of leptin and leptin receptor in breast tumors and its association with tumor aggressiveness suggest that leptin can also influence breast tumor growth and progression via an autocrine pathway." (PMID 26359358, 2015). "A high level of leptin has been linked to both breast tumor aggressiveness and poor prognosis." (PMID 36562831, 2023). "Our data indicates that autophagy inhibition could represent an alternative to relieve key events in breast tumor progression associated with elevated levels of leptin in obese individuals." (PMID 33763424, 2021). "In line with this, the upregulation of leptin and its receptor have been associated with early stages of carcinogenesis, particularly in patients with in situ ductal carcinoma compared with invasive breast carcinoma, suggesting that leptin and its receptor can promote the breast tumour progression." (PMID 39408212, 2024). "Studies have demonstrated that leptin affects the growth of breast tumors both directly by interacting with breast tumor cells and indirectly by impacting different elements of the TME." (PMID 39040042, 2024). "Visceral adipose tissue (VAT) is known to produce leptin, but the effect of locally generated leptin from breast fat tissue compared to circulating leptin on breast tumour progression is not well understood." (PMID 39251829, 2024). "This study is a scientific approach to the interaction between the tumor microenvironment rich in adipocytes and the influence of leptin on the development of breast tumors with an unfavorable prognosis (HER2 positive and triple negative)." (PMID 35989732, 2022). "Exogenous leptin abrogates tamoxifen-mediated growth inhibition and potentiates breast tumor growth even in the presence of tamoxifen." (PMID 34389732, 2021). "We next explored a potential link between changes in fatty acid metabolism and well‐characterized effects of leptin on breast tumor growth." (PMID 33226729, 2021). "Adiponectin administration in breast tumor-bearing mice exposed to leptin results in reduced Med1 expression in breast tumors indicating that strategies to elevate adiponectin level in obese state can be beneficial." (PMID 34389732, 2021). "We found that obese/hyperleptinemic tumor bearing mice did not respond to tamoxifen treatment and showed increased tumor progression implying that leptin renders breast tumors refractory to tamoxifen." (PMID 34389732, 2021). "Our results contradict previous research that indicates the involvement of serum LEP in the progression of established breast tumors." (PMID 34414945, 2021). "We demonstrated that an increased FGFR1 copy number variation was significantly correlated with an increased leptin copy number in both ER+ breast tumors (7.8 × 10−5, beta coefficient 0.0367) and ER- breast tumors (6.5 × 10−7, beta coefficient 0.1798)." (PMID 33019728, 2020).